KRTAP10-4 (keratin associated protein 10-4)
Description:
In the hair cortex, hair keratin intermediate filaments are embedded in an interfilamentous matrix, consisting of hair keratin-associated proteins (KRTAP), which are essential for the formation of a rigid and resistant hair shaft through their extensive disulfide bond cross-linking with abundant cysteine residues of hair keratins. The matrix proteins include the high-sulfur and high-glycine-tyrosine keratins.
Synonyms: KAP10.4; KAP18-4; KRTAP10.4; KRTAP18-4; KRTAP18.4
Tractability: No criterion of Open Targets' tractability assessment is met for any kind of drug.
Gene: Protein-coding gene on chromosome 21 (44,573,729 to 44,575,371, forward strand). Ensembl gene ENSG00000215454.
Pathways (Reactome):
Developmental Biology: Keratinization
Gene Ontology:
Molecular function: protein binding
Cellular component: cytosol; keratin filament
Genetic constraint (gnomAD): Loss-of-function variants: 0 observed, 0.55 expected, observed/expected ratio (o/e) 0, 90% interval 0 to 1.83. That is too few expected variants to judge how well the gene tolerates losing a copy. Missense variants: 374 observed, 444.48 expected, observed/expected ratio (o/e) 0.84, 90% interval 0.77 to 0.92. Synonymous variants: 147 observed, 173.29 expected, observed/expected ratio (o/e) 0.85, 90% interval 0.74 to 0.97.
Homologues: Orthologues: rat Krtap10-9 (46% identical), rat Krtap10-1 (43% identical), rat LOC120098854 (43% identical), mouse Krtap10-32 (42% identical), mouse Krtap10-33 (41% identical), mouse Krtap10-34 (38% identical), mouse Krtap10-30 (38% identical), rat Krtap10-10l2 (38% identical), rat Krtap10-1l1 (38% identical), mouse Gm49918 (37% identical), mouse Krtap10-29 (37% identical), mouse Krtap10-27 (37% identical), and 35 more. Paralogues in human: KRTAP10-7 (80% identical), KRTAP10-6 (59% identical), KRTAP10-9 (59% identical), KRTAP10-11 (58% identical), KRTAP10-5 (55% identical), KRTAP10-12 (53% identical), KRTAP10-2 (51% identical), KRTAP10-1 (50% identical), KRTAP10-10 (45% identical), KRTAP10-8 (45% identical), KRTAP10-3 (43% identical), KRTAP16-1 (26% identical), and 35 more.